TIGIT (T cell immunoreceptor with Ig and ITIM domains)
Diseases named in the same sentence as TIGIT in open-access papers (continued):
Sharing a sentence is not in itself a finding about the gene and the disease.
colon carcinoma (50 papers, 2018 to 2025). "In contrast to CTLA-4 and PD-1 checkpoint molecules, TIGIT is associated with NK cell exhaustion in mice with tumors and patients with colon cancer." (PMID 40567374, 2025). "noticed that TIGIT was associated with NK cell depletion in tumor-bearing mice and colon cancer patients." (PMID 41246355, 2025). "For example, CD39+ Tregs in gastric and colon cancer were identified as a potentially important immunosuppressive subset, and a higher number of TIGIT+Foxp3+ γδ T cells was associated with poor overall survival in patients with acute myeloid leukemia (AML)." (PMID 36901957, 2023). "On naïve T cells, TIGIT is expressed only upon activation, while on NK cells it is constitutively expressed and its up-regulation in tumor-bearing mice and patients with colon cancer was associated with NK cell exhaustion." (PMID 37760586, 2023). "TIGIT is associated with NK cell depletion in tumor-bearing mice and patients with colon cancer, and this depletion is restored by its blockade, thereby stimulating strong anti-tumor immunity." (PMID 35606854, 2022). "Conversely to CTLA-4 and PD-1, TIGIT was associated to NK-cell exhaustion in a mouse model of colon cancer and TIGIT blockade was capable of reverting the condition allowing NK cells to trigger an anti-tumor immune response." (PMID 33255582, 2020). "TIGIT was associated with exhaustion of NK cells in tumor-bearing mice and colonic cancer patients, while this exhaustion was reverted by its blockade, thereby eliciting potent antitumor immunity." (PMID 32117298, 2020). "TIGIT has been linked to NK cell exhaustion in some cancers, such as colon cancer." (PMID 39201462, 2024). "Notably, PRS exhibited a significant positive correlation with mRNA levels of immune checkpoint-associated molecules CD274, CTLA4, LAG3, and TIGIT in colon cancer tissues." (PMID 38577604, 2024). "Despite the promising results obtained with TIGIT blockade in various cancers, anti-TIGIT monotherapy has been reported to be insufficient to cause the regression of already established tumors in mouse models of colon carcinoma and glioblastoma." (PMID 35327475, 2022). "Increased expression of TIGIT on NK-cells in the peripheral blood has been reported in patients with myelodysplastic syndrome, high risk non-muscle invasive bladder cancer and gastrointestinal cancer (gastric and colon cancer)." (PMID 34276685, 2021). "They found that treatment with a monoclonal antibody against TIGIT in models of colon cancer, breast cancer, and melanoma resulted in increased NK cell infiltration and significant inhibition of tumor growth." (PMID 41246355, 2025). "The PRS exhibited a significant positive correlation with the infiltration of diverse immune cells, expression levels of related cytokines, and mRNA levels of immune checkpoints CD274, CTLA4, LAG3, and TIGIT in colon cancer tissues." (PMID 38577604, 2024). "Second, efficacy for ZGGS15 (only the anti-TIGIT part is active in this model) plus anti-PD-1 in the BALB/c-hPD-1/hTIGIT mouse bearing CT26 colon cancer model was performed." (PMID 38724599, 2024). "In mice bearing tumors, including colon tumors, breast tumors and chemically induced fibrosarcomas, treatment with an mAb to TIGIT induced tumor growth inhibition and tumor volume reduction and prevented NK-cell exhaustion." (PMID 36960057, 2023). "Next, we examined the expression of TIGIT in the distant tumor environment following MWA treatment in the MC38 colon cancer model." (PMID 35320940, 2022). "TIGIT expression was shown to be significantly higher on NK cells derived from the intratumoral region of patients with colon cancer, compared to NK cells from the tumor-surrounding tissue." (PMID 35327475, 2022). "BALB/c mice were subcutaneously injected with murine MSS CT26 colon tumor cells, followed by treatment with rat IgG, anti-TIGIT mAb (10 mg/kg), OX (1.5 mg/kg) or anti-TIGIT mAb plus OX on day 8 post-tumor challenge." (PMID 36389751, 2022).
colon carcinoma (continued). "In the MC38 colon carcinoma mouse model, TIGIT blockade alone led to a small but uniform retardation of tumor growth." (PMID 34367161, 2021). "Blockade of TIGIT, in colon cancer-bearing mice, prevents NK cell exhaustion and promotes a potent tumor-specific T cell immunity in an NK cell-dependent manner." (PMID 34975867, 2021). "Taken together, these data indicate that VV-α-TIGIT has a better anti-tumor effect than VV-Control in colon cancer models." (PMID 33581644, 2021). "Patients with colon cancer show higher TIGIT expression on NK-cells in intratumoral regions than in peritumoral regions." (PMID 34276685, 2021). "TIGIT is a checkpoint receptor which mediates T and NK cell exhaustion in tumor-bearing mice and in patients with colon cancer." (PMID 34975867, 2021). "Seven checkpoint-related genes (BTLA,CD80, CD86, CTLA4, IDO1, PDCD1LG2, and TIGIT) had decreased expression in the KRAS-mutated group, providing potential opportunities for immunotherapy in colon cancer." (PMID 33254149, 2020). "TIGIT expression on NK cells, and the consequent exhaustion of these cells, has recently been described in colon cancer patients and tumor models." (PMID 33255582, 2020). "Anti-TIGIT plus anti-PD-L1 blockade prevented the exhaustion of NK cells in tumor-bearing mice and colon cancer patients." (PMID 32117298, 2020). "TIGIT is mainly upregulated on T cells, however higher expression of TIGIT has also been found on NK cells in intratumoral regions in colon cancer." (PMID 33260925, 2020). "Some checkpoint-related genes (BTLA, CD80, CD86, CTLA4, IDO1, PDCD1LG2, and TIGIT) had decreased expression in the KRAS-mutated group, providing potential opportunities for immunotherapy in colon cancer." (PMID 33254149, 2020). "NK cell-specific TIGIT KO in mice results in significantly prolonged survival, while TIGIT blockade inhibits NK cell exhaustion in colon tumors, breast tumors, and MCA-induced fibrosarcomas." (PMID 31681269, 2019). "The function of intrinsic TIGIT in colon cancer cells was investigated by using the CRISPR/Cas9 knockout model." (PMID 30555485, 2018). "To study the function of TIGIT, we examined the expression in murine colon cancer cell lines, and unexpectedly discovered its intrinsic expression." (PMID 30555485, 2018). "Here, we found TIGIT was over-expressed in colon cancer tissues compared with adjacent normal tissues." (PMID 30555485, 2018). "Moreover, in an MC38 colon tumor mouse model, animals treated with dual anti-TIGIT/PD-1 antibodies exhibited heightened secretion of IFN-γ by CD4+ TILs in comparison to those treated solely with anti-PD-1 therapy." (PMID 38375475, 2024). "Moreover, our constructed humanized Tri-NAb (Hu Tri-NAb) targeting human PDL1, 4-1BB, and TIGIT displayed remarkable efficacy against patient-derived colon cancer organoids and effectively suppressed HT-29 human colon cancer growth in humanized mice." (PMID 39043643, 2024). "Furthermore, we found that the combination of MWA and anti-TIGIT treatment prolonged the survival of mice with MC38 colon cancer and inhibited tumor growth." (PMID 35320940, 2022). "Likewise, in the CT26 colon carcinoma and glioblastoma mouse models, co-blockade of TIGIT and PD-1/PD-L1 pathway synergistically decreased tumor burden and improved survival by increasing IFN-γ+ CD8+ TILs." (PMID 34367161, 2021). "Moreover, animals treated with dual anti-TIGIT/PD-1 antibodies showed increased IFN-γ secretion by CD4+ TILs in the MC38 colon tumor mouse model, compared to single anti-PD-1 treatment." (PMID 34367161, 2021). "However, it has been shown that Fap2 protein derived from Fusobacterium nucleatum present in human colon can interact with TIGIT to inhibit NK cytotoxicity against colon cancer." (PMID 32195317, 2020). "We generated ex vivo tumor slice cultures from fresh surgical resections of gastric and colon cancer and treated them with GITR agonist or TIGIT antagonist antibodies." (PMID 38008725, 2023).
colon carcinoma (continued). "TILs from MC-38 cell-derived colon tumors and splenic lymphocytes exhibited high levels of the T-cell exhaustion markers including PD-1, 2B4, TIM3+ and TIGIT and similar results were observed in the spleen, and these were inhibited by NR4A1 antagonists." (PMID 37847301, 2023). "Blockade of TIGIT inhibited tumor growth and prevented exhaustion of tumor-infiltrating NK cells in the CT26 colon carcinoma mouse model." (PMID 34367161, 2021). "TIGIT knockout or Ab blockade led to increased IFN-production and enhanced CD8+T cells' and NK cells' anti-tumor effects, resulting in colon cancer growth inhibition." (PMID 32714324, 2020). "Moreover, blockade of TIGIT or an anti-TIGIT antibody enhances T cell activation and restores CD8+ T exhaustion, enhancing antitumor activity in gastric cancer, colon cancer, myeloma, and head and neck squamous cell carcinoma." (PMID 34433460, 2021). "Considering that low-dose OX, but not CIS, showed synergistic antitumor effects with TIGIT blockade, we hypothesized that low-dose OX sensitized colon tumors to checkpoint blockade therapy." (PMID 36389751, 2022). "Recently, Tian's team demonstrated for the first time that only TIGIT is associated with NK cell exhaustion, but not the other checkpoint molecules, and that blocking TIGIT could enhance the anti-tumor responses of NK cells in colon cancer." (PMID 30364127, 2018). "In the pre-clinical mice TIGIT negative mice bearing colon cancer (MC38 model), co-blockade of TIGIT and PD-1 was associated with enhanced effector cell functions of both CD4+ and CD8+ T cells compared to either therapy alone; and TIGIT/PD-1 co-blockade produced a 100% cure rate." (PMID 37569880, 2023). "An investigation showed that TIGIT, rather than CTLA-4 or PD-1, was a remarkable factor in NK cell exhaustion in tumor-bearing mice and colon cancer patients." (PMID 40567374, 2025).
myeloma (50 papers, 2019 to 2025). "The results of examining NK cells isolated from multiple myeloma (MM) patients also show that these cells have exhausting markers, and the level of TIGIT in them is associated with an increase compared to healthy control." (PMID 38515166, 2024). "High expression of TIGIT is predictive of tumor progression in multiple myeloma and is associated with poor outcomes and resistance to PD-1 immune checkpoint inhibitors in follicular lymphoma." (PMID 38785789, 2024). "Recently, the progression of myeloma has been associated with high levels of TIGIT expression on CD8+ T cells, which exhibit impaired proliferative and cytokine responses upon antigen stimulation." (PMID 35886976, 2022). "They observed also that in both mice and humans high levels of TIGIT expression on CD8+ T cells were associated with multiple myeloma progression, suggesting the development of TIGIT− blocking strategies in these patients." (PMID 33782477, 2021). "CD8+ T cells expressing high levels of TIGIT on their surfaces were associated with multiple myeloma progression." (PMID 32117298, 2020). "Notably, TIGIT deficiency or blockade has demonstrated protection against multiple myeloma in mice, and heightened effector activity of CD8+ T lymphocytes in myeloma patients." (PMID 39939322, 2025). "TIGIT has also been implicated in loss of myeloma specific immunity leading to disease progression." (PMID 38322418, 2024). "Moreover, TIGIT-deficient mice show increased survival when challenged with VK*MYC myeloma cell lines; however, a recent study revealed that TIGIT-deficient mice did not reject the implanted B16F10 and MC38 more efficiently compared with wild-type (WT) mice." (PMID 33670993, 2021). "TIGIT represents a potent inhibitor of myeloma-specific immunity, and these results reveal a novel mechanism of action through which this immune checkpoint inhibitor can favor tumor escape." (PMID 39858045, 2025). "Using a myeloma model, our in vitro studies showed that a (combined) blockade of TIGIT and CD39 leads to increased lysis of tumor cells." (PMID 40274631, 2025). "Using a myeloma model, functional in vitro studies showed that blockade of TIGIT and CD39 leads to increased PBMC-mediated lysis of myeloma cells." (PMID 40274631, 2025). "The cytotoxic assays showed an increased PBMC-mediated lysis of myeloma cells using a single blockade or combining blockade of TIGIT and CD39." (PMID 40274631, 2025). "Not consistent with previous studies, although the expression of PD-1 on CD4+ T cells was elevated in myeloma patients with severe COVID-19, the expression of TIGIT was instead decreased during the acute phase." (PMID 39355257, 2024). "TIGIT blockade in combination with immunomodulators has been proposed as an exciting treatment modality to restore myeloma immunity." (PMID 38322418, 2024). "So, it proposed that blocking TIGIT can restore NK cell exhaustion and provide a potential avenue for antitumor immunotherapy for multiple myeloma patients." (PMID 38515166, 2024). "In a preclinical study, the anti-TIGIT antibody was more effective than the control and anti-PD-1 antibody in reducing myeloma burden and prolonging mice survival." (PMID 38410372, 2024). "Monoclonal antibodies (mAbs) are capable of suppressing TIGIT, thus hindering the development of multiple myeloma (MM)." (PMID 37647290, 2023). "TIGIT+ CD8+ T cells from patients with AML, GC, or multiple myeloma showed reduced cytokine production, high susceptibility to apoptosis, and significantly reduced proliferation and killing ability." (PMID 37670328, 2023). "TIGIT appears to be a potent inhibitor of myeloma-specific immunity and represents a promising new checkpoint target." (PMID 36512425, 2023). "Collectively, these data provide a logical rationale for combining TIGIT inhibition with immunomodulatory drugs to prevent myeloma progression after ASCT." (PMID 36512425, 2023).
myeloma (continued). "TIGIT+ T cells originating from MM patients are characterized by decreased proliferation and inability to secrete cytokines in response to myeloma antigen stimulation." (PMID 38213954, 2023). "In a syngeneic, immunocompetent multiple myeloma mouse model, blockade of TIGIT synergized with LEN maintenance by inducing immune protection, characterized in part by the expansion of polyfunctional T cells in the bone marrow." (PMID 36787254, 2023). "We have previously demonstrated that CD8+ T cells are the major mediators of myeloma-specific T cell responses and that TIGIT inhibition activates CD8+ T cells after SCT." (PMID 36512425, 2023). "Here we demonstrate high expression of TIGIT on activated CD8+ T cells in mobilized peripheral blood stem cell grafts from patients with myeloma." (PMID 36512425, 2023). "In mice bearing MM tumors, TIGIT expression in CD8+ T cells correlated with myeloma burden, and was detected on 30–40% of FOXP3+ Tregs." (PMID 35327475, 2022). "In an in vitro study, TIGIT blockade depleted FoxP3+ Tregs while increasing proliferation of IFNγ-producing CD4+ T cells from peripheral blood from patients with multiple myeloma." (PMID 34367161, 2021). "Recent studies found that TIGIT-blocking antibodies or TIGIT knockout potentiated anti-myeloma responses in mouse models, although this was primarily attributed to TIGIT expression suppressing the activation capacity of CD8+ T cells." (PMID 33435153, 2021). "In multiple myeloma (MM) mouse tumor model, TIGIT blockade leads to reduced tumor growth and increased survival compared with mice receiving control IgG or anti-PD-1 mAbs." (PMID 33670993, 2021). "In Vk*MYC TIGIT-null mice, myeloma growth was delayed, and in wild type mice, tumor burden was reduced with anti-TIGIT treatment." (PMID 33562441, 2021). "The same study investigated the anti-TIGIT mAb in an in-vivo model and showed that the anti-TIGIT mAb decreased myeloma disease burden in the BM and prolonged survival compared with control-Ig, or anti-PD-1 mAb-treated mice." (PMID 33304346, 2020). "TIGIT blockade prevented the T-cell exhaustion mechanism responsible for myeloma escape after stem cell transplantation." (PMID 32117298, 2020). "Previously, TIGIT was reported to be highly expressed on CD8+ T cells in myeloma, indicating that TIGIT mainly acts on T cells by regulating CD8+ T cells." (PMID 32903786, 2020). "In MM patients, especially those with relapsed/refractory MM (RRMM), co-inhibitory molecules including PD-1 and TIGIT are upregulated on activated T-cells, which protects myeloma cells from immune attack by directly interacting with their ligand expressed in myeloma cells." (PMID 39087026, 2024). "Additionally, the expression of CD155, a TIGIT high-affinity ligand in multiple myeloma (MM) cells, was decreased by the mTOR signaling pathway." (PMID 37239949, 2023). "In addition, CD8+ T cells in patients with AML or multiple myeloma with high-TIGIT expression expressed lower levels of CD226." (PMID 37670328, 2023). "Furthermore, the combination of TIGIT inhibition with IMiDs provided synergistic myeloma control, presenting a logical approach to augment PFS after transplantation." (PMID 36512425, 2023). "In fact, the expression of the checkpoint inhibitory molecules PD-1, TIM3, LAG3, and TIGIT has long been associated with lack of T-cell fitness and increased incidence of multiple myeloma relapse." (PMID 36874402, 2022). "TIGIT was found to induce myeloma immune escape after transplantation, and blocking TIGIT could overcome tumor progression." (PMID 33597728, 2021). "Thus, the role of TIGIT-Nectin-2 interaction in myeloma progression and its relevance as therapeutic target in patients with SMM remains to be elucidated." (PMID 34880879, 2021).